FOXO1 (forkhead box O1)
Diseases named in the same sentence as FOXO1 in open-access papers (continued):
Sharing a sentence is not in itself a finding about the gene and the disease.
atherosclerosis (continued). "In addition, METTL14 was demonstrated to directly bind to FOXO1 mRNA and enhance FOXO1 mRNA translation by increasing its m6A modification, which thereby increases adhesion molecule expression, aggravating endothelial inflammation, and contributes to atherosclerosis development." (PMID 35718942, 2022). "Macrophage polarization plays an essential role in atherosclerosis, and M1 polarization and inflammation are generated by PAR2 activation via the FOXO1-dependent pathway." (PMID 35607519, 2022). "FOXO1 and its gene expression as well as SIRT1 and HSP72 were suggested as predictors of early detection of premature atherosclerosis, but as far as our knowledge, our team was the first to prove such results in β-TM patients." (PMID 36289866, 2022). "Another m6A writer, METTL14, has been shown to interact with FOXO1 and act directly on the promoter regions of VCAM-1 and ICAM-1, which enhanced the binding of monocytes to endothelial cells during atherosclerosis." (PMID 34869371, 2021). "This is consistent with our findings, which demonstrated that the expression of FOXO1 in METTL14 knockdown mice was reduced and the development of atherosclerosis was significantly inhibited." (PMID 32802173, 2020). "Previous studies have indicated that macrophage regulation involves the FABP4 and FOXO1 pathways in an atherosclerosis model; however, these mechanisms have not been confirmed in a DN model, representing a critical gap in the literature." (PMID 41471323, 2025). "FOXO1 respectively inhibits and enhances eNOS and inducible-NOS (iNOS), contributing to pro-atherogenic effects, as confirmed by the reduced progression of atherosclerosis in FOXO1-deleted mouse models." (PMID 40651947, 2025). "Interestingly, METTL14 has been reported to promote vascular endothelial cell proliferation and inflammation by increasing the m6A methylation modification of pre-miR-19a and forkhead box O1 (FOXO1), respectively, thus contributing to atherosclerosis." (PMID 36093141, 2022). "Interacting with FOXO1, METTL14 acts directly on the promoter regions of ICAM-1 and VCAM-1 to upregulate their transcription, thereby mediating the inflammatory response of endothelial cells in atherosclerosis." (PMID 36482903, 2022). "Besides, METTL14 interacted with FOXO1 and acted directly on the promoter regions of VCAM-1 and ICAM-1, which enhanced monocyte binding to endothelial cells during atherosclerosis." (PMID 34869371, 2021). "FOXO1 enhances the release of pro-inflammatory cytokines and controls macrophage oxLDL uptake and vascular calcification, consequently, senescent CD8+ CD28− T cells might slow atherosclerosis via SIRT1/FOXO1 decline." (PMID 38138958, 2023). "Additionally, FOXO1 has indispensable role in positive regulation of adipocyte fatty acid binding protein (FABP4) gene transcription, thereby controlling uptake and accumulation of lipids in macrophages, and promoting atherosclerosis." (PMID 26956801, 2016).
lung cancer (44 papers, 2012 to 2025). A malignant neoplasm involving the lung. "Inhibition of FOXO1 nuclear export restores sensitivity to AKT-associated erlotinib resistance in lung cancer cells." (PMID 32948132, 2020). "According to earlier studies, FUT4 may prevent cisplatin resistance in lung cancer from being caused by FOXO1-induced apoptosis." (PMID 38343056, 2024). "Such as miR-411 in lung cancer downregulates FOXO1, further influencing cell proliferation and cell survival in lung cancer." (PMID 38245694, 2024). "Overexpression of LncRNA LINC00261 inhibits the growth and metastasis of lung cancer by modulating the miR-1269a/FOXO1 axis, in which miR-1269a serves as a carcinogenic miRNA." (PMID 37264406, 2023). "ROC curve analysis indicated a relatively high diagnostic value of FOXO1 for LUAD, LUSC and lung cancers." (PMID 37932766, 2023). "We first analyzed the expression of FOXO1 in 16 lung cancer tissues with adjacent tissues by qRT-PCR, and found that the expression of FOXO1 in lung cancer tissues was lower than that in adjacent tissues." (PMID 37932766, 2023). "Knockdown of FOXO1 in lung cancer cells downregulated the activation of AKT, and the AKT activation was not restored by circHERC1 overexpression." (PMID 37932766, 2023). "In mechanism, the interaction between AKT and TRIB3 was necessary for the FOXO1/AKT/SOX2 activation in lung cancer." (PMID 35473511, 2022). "The expression of LINC00261 is down-regulated in lung cancer, and the overexpression of LINC00261 inhibits the growth and metastasis of lung cancer by regulating the miR-1269a/FOXO1 axis." (PMID 35252180, 2022). "SIRT1 repression increases cellular levels of acetylated FOXO1 that transcriptionally activates apoptotic signaling in the lung cancer cells." (PMID 31689236, 2019). "Elevated Prx 1 induced resistance to docetaxel treatment through suppression of FOXO1-induced apoptosis in lung cancer A549 xenograft tumors." (PMID 31470801, 2019). "FoxO1 acetylation promotes cell apoptosis in pancreatic cancer cells; whereas FoxO3a deacetylation up-regulates expression of proapoptotic proteins in lung cancer cells." (PMID 28903430, 2017). "In contrast, in our study FOXO1 translocation was completely inhibited in U-2 OS cells pretreated with the antioxidant NAC, suggesting that induction of oxidative stress by BITCs is required for the FOXO1 translocation, as also shown for lung cancer cells." (PMID 27622707, 2016). "ZBTB20 (also known as DPZF, HOF, and ZNF288), which belongs to the BTB/POZ zinc finger family of proteins, represses forkhead box O1 (FoxO1) expression in lung cancer cells and promotes cell growth." (PMID 27183310, 2016). "FOXO1 expression was associated with an earlier stage of lung cancer, the less nodal involvement or venous invasion, or a favorable prognosis in NSCLC where apoptosis was induced by FOXO1." (PMID 26289446, 2015). "Our study clarifies a new mechanism of erlotinib through regulation of miR-9 - Foxo1 in lung cancer and suggests targeting miR-9 to enhance the anticancer efficacy of erlotinib." (PMID 26593208, 2015). "While FOXO1 traditionally acts as a tumor suppressor, its regulation and function in lung cancer are complex, influenced by intricate networks of signaling pathways, post-transcriptional modifications, protein stability, and interactions with upstream regulators." (PMID 39201328, 2024). "More importantly, we found that circHERC1 could bind to FOXO1 and sequester it in the cytoplasm, thereby promoting the proliferation of lung cancer cells." (PMID 37932766, 2023). "From TCGA data, we also found that FOXO1 was down-regulated in lung cancer tissues." (PMID 37932766, 2023).
lung cancer (continued). "FUT4 may also be related to multidrug resistance in lung cancer and may participate in chemoresistance to cisplatin by suppressing FOXO1-induced apoptosis in lung cancer." (PMID 37256139, 2023). "In addition, another study that explored curcumin-induced FOXO1 inhibition of lung cancer progression and metastasis found that activation of FOXO1 inhibited the spread of lung cancer cells by downregulating CCND1 gene expression." (PMID 36670858, 2023). "In lung cancer, FOXO1 repression by miR-183 is described as an anti-apoptotic mechanism." (PMID 35486213, 2022). "Foxo1 was previously identified as a direct target of miR-411 in lung cancer cells." (PMID 36317138, 2022). "Interestingly, CD44 and FOXO1 transcripts were observed to be down-regulated in primary lung cancer but significantly up-regulated in lung cancer patients with bone metastasis." (PMID 36424413, 2022). "Above results showed an abnormal expression of FOXO1 in lung cancer tissues and cells." (PMID 31217928, 2019). "We suspected that FOXO1 might be involved in regulating the biological processes of lung cancer cells." (PMID 31217928, 2019). "Taken together, these results indicate that miR-196 plays a critical role in the pathogenesis of lung cancer, and that at least some of the oncogenic activities of miR-196a may depend on suppression of the expression of the transcription factor FoxO1 and/or the cyclin-dependent kinase inhibitor p27." (PMID 27880728, 2017). "These GO terms encompass six genes relevant to lung cancer found primarily in “Pathways in cancer” GO and partially overlapping with two other GOs: FLT3, FOXO1, CSF1R, RUNX1, PPARG, and TGFBR2." (PMID 39201328, 2024). "We also conducted EdU, apoptosis and transwell assays to detect the rescue of FOXO1 and HMGB1 knockdown on cell proliferation, apoptosis, migration and invasion in circHERC1 overexpressing lung cancer cells." (PMID 37932766, 2023). "Meanwhile, activated TRIB3 interacted with AKT to upregulated FOXO1 and SOX2 expression, resulting in sustained tumor progression in lung cancer." (PMID 35473511, 2022). "Based on transcript level expression study using quantitative real-time PCR showed five significantly differentially expressed genes SPP1, VEGFA, CD44, FOXO1 and POSTN in EVs cargo derived from lung cancer patients with bone metastasis." (PMID 36424413, 2022). "In lung cancer, TFP inhibited FOXO1 nuclear export and restored sensitivity to Erlotinib resistance by modulating the KLF6/FOXO1 signaling cascade in both cell culture and xenograft models." (PMID 31572198, 2019). "Using serum-starved (24 h) or H2O2-treated (0.5 mM, 6 h) H1299 human lung cancer and HCT-116 human colon cancer cells as experimental models, FoxO1 was identified as a mediator of autophagy." (PMID 22457718, 2012). "In The Cancer Genome Atlas (TCGA), a low expression of FOXO1 decreased the survival rate not only in lung adenocarcinoma, but also lung cancer (all), whereas a high expression of CGN decreased the survival rate in lung cancer (all)." (PMID 38338691, 2024). "These in vivo findings in ectopic xenograft mouse models were consistent with the in vitro observations, and hence support that overexpression of circHERC1 can promote in vivo tumorigenicity of lung cancer cells via the miR-142-3p-HMGB1 axis and interaction with FOXO1." (PMID 37932766, 2023). "Quantitative gene expression of SPP1, VEGFA, POSTN, RUNX2, CD44, and FOXO1 from lung cancer patients with and without bone metastasis normalized against healthy control." (PMID 36424413, 2022).
pancreatic cancer (43 papers, 2010 to 2025). "The increase of FoxO1 caused by pancreatic cancer-derived exosomes contributed to inhibiting the translocation of GLUT4 to the plasma membrane." (PMID 33816504, 2021). "Interestingly, a study on pancreatic cancer patients with weight loss found that the expression of FoxO1 and −3 was even decreased in skeletal muscle biopsies compared to controls." (PMID 26856534, 2016). "Importantly, both Egr-1 and Ier5 were recently identified as cachexia-associated genes upregulated in muscles of pancreatic cancer patients together with Foxo1." (PMID 25539728, 2014). "FoxO1 is a crucial autophagy-inducing factor that exhibits abnormal expression in diverse tumor cells, encompassing pancreatic cancer." (PMID 41150819, 2025). "In other contexts, erianin activates ROS-mediated apoptosis and inhibits JAK/STAT signaling in esophageal carcinoma, while in pancreatic cancer it modulates the AKT/FOXO1 and ASK1/JNK/p38 MAPK pathways to suppress proliferation and migration." (PMID 41154521, 2025). "For instance, Erianin inhibited the pancreatic cancer cell proliferation through AKT/FOXO1 and ASK1/JNK/p38 MAPK signaling pathways." (PMID 39605083, 2024). "The authors present a model in which FOXO1 inhibits the TCF4/beta‐catenin interaction in pancreatic cancer via induction of LINC01197." (PMID 37584250, 2023). "Researchers have found that autophagy induced by cytosolic FOXO1 is capable of suppressing tumor and that, in pancreatic cancer, miR-138-5p inhibits autophagy by blocking the SIRT1/FoxO1/Rab7 axis." (PMID 33828486, 2021). "For example, it has been reported that capsaicin treatment induces CBP and represses SIRT1 expression, resulting in an increase in FOXO1 acetylation to limit pancreatic tumour growth." (PMID 32372224, 2020). "The chilli pepper extract capsaicin activates JNK to induce FOXO1 acetylation for Bim-induced apoptosis in pancreatic cancer." (PMID 32372224, 2020). "FoxO1, encoding a transcription factor, was up-regulated in its mRNA and protein levels in the PARP1-KO Ewing sarcoma RD/KO1, Cri/KO, and SK/KO1 cells and pancreatic cancer CAPAN1/KO cells." (PMID 31992690, 2020). "In pancreatic cancer cells, curcumin has been reported to induce FoxO1 expression in pancreatic cancer cells by acting on PI3K/Akt signaling, which caused cell cycle arrest and apoptosis induction." (PMID 31590362, 2019). "Pancreatic cancer cells treated with curcumin, presented an increased in FOXO1 (Forkhead box O1) expression, which is correlated with inhibition in phosphorylation/activation of PI3K and Akt." (PMID 27834913, 2016). "The inhibitory effects of SFN on cell viability were further enhanced when pancreatic cancer cells were transfected with FOXO1, FOXO3a, and FOXO4." (PMID 20642839, 2010). "In addition, the compound BRT modulates the AKT-FOXO1 signaling axis in human pancreatic cancer cells, decreasing the level of phospho-AKT and inducing nuclear accumulation of the transcription factor FOXO1 in AsPC-1 and Panc-1 pancreatic cancer cells." (PMID 34680439, 2021). "Except TET1, other molecular mechanisms inhibiting Wnt signaling in pancreatic tumor like FOXO1-related LINC01197 has been reported, these mechanisms may contributes the final activity of Wnt signaling pathway in pancreatic tumor." (PMID 31399111, 2019). "In the current study, we found that downregulation of miR-138-5p was associated with induced autophagy in human pancreatic cancer tissues; however, restored expression of miR-138-5p inhibited the SIRT1/FoxO1/Rab7 pathway-dependent autophagy and subsequent apoptotic cell death." (PMID 28052003, 2017). "Our research indicates that SIRT1 and FoxO1 may synergistically mediate autophagy under metabolic stress by forming a functional complex in pancreatic cancer cells." (PMID 28052003, 2017).
pancreatic cancer (continued). "Since inhibition of FOXO1 (FKHR) transcription factor enhanced resveratrol-induced apoptosis in pancreatic cancer cells, we sought to examine whether resveratrol enhances translocation of wild type and phosphorylation deficient mutant of FOXO1 to nucleus." (PMID 21980390, 2011). "In order to examine whether FOXO transcription factors affect the ability of SFN to inhibit cell viability, pancreatic cancer cells were transfected with FOXO1, FOXO3a or FOXO4." (PMID 20642839, 2010). "In particular, Acvr2b, FoxO1, and STAT3 all had spearman correlations of at least 0.63 with three of these weights indicating that both the transcriptions factors and TGFβ signaling may play a role in pancreatic cancer associated cachexia." (PMID 30513792, 2018). "In one study on patients with pancreatic cancer and weight loss, decreased protein levels and activation of Akt, mTOR, p70S6K, GSK3-ß and FoxO1 were observed in skeletal muscle tissue compared to samples from patients with pancreatic cancer without weight loss." (PMID 26856534, 2016). "In pancreatic cancer, the PI3K-AKT can promote the binding of p-FOXO1 with 14-3-3 proteins to block apoptosis." (PMID 34970413, 2021). "Pancreatic cancer PANC-1 and MIA PaCa-2 cells were stably transfected with plasmids expressing FOXO1, FOXO3a and FOXO4 shRNA." (PMID 21980390, 2011). "Thus, the binding of ALA to MrgD in pancreatic cancer cell lines induces an antiproliferative effect by inhibiting the BRAF–MKK–ERK and PI3K–AKT pathways and activating FoxO1." (PMID 38338778, 2024). "FOXO1 was overexpressed using an integrated, selected virally transduced cassette, leading to induction in the gene expression of a long noncoding RNA LINC01197 in a series of pancreatic cancer cell lines AsPC1, BxPC3, and PANC1." (PMID 37584250, 2023).